RNU6-202P (RNA, U6 small nuclear 202, pseudogene)
Gene: Small nuclear RNA gene on chromosome X (41,919,254 to 41,919,349, reverse strand). Ensembl gene ENSG00000251807.
Homologues: Orthologues: chimpanzee U6 (100% identical), macaque U6 (97% identical), dog U6 (89% identical), pig U6 (89% identical), rabbit RNU6-202P (84% identical), guinea pig RNU6-202P (80% identical), rat LOC120096097 (64% identical), mouse Gm23341 (58% identical), mouse Gm24129 (53% identical). Paralogues in human: RNU6-393P (79% identical), RNU6-961P (78% identical), RNU6-1031P (77% identical), RNU6-1075P (77% identical), RNU6-1085P (77% identical), RNU6-1145P (77% identical), RNU6-1316P (77% identical), RNU6-160P (77% identical), RNU6-16P (77% identical), RNU6-326P (77% identical), RNU6-940P (77% identical), RNU6-1335P (76% identical), and 1287 more.